MMP1 (matrix metallopeptidase 1)
Diseases named in the same sentence as MMP1 in open-access papers (continued):
Sharing a sentence is not in itself a finding about the gene and the disease.
oral cancer (32 papers, 2007 to 2026). "A meta-analysis on the association of risk of oral cancer with MMP polymorphisms had identified MMP-1 (-1607) as a significant genetic marker related to oral cancer risk in Asian and protectiveness in European groups." (PMID 33681393, 2021). "We identified that even one variant allele of the MMP-1 gene increases the risk of having an oral cancer diagnosis in Puerto Rico." (PMID 24278120, 2013). "Another report also suggested involvement of the MMP-1(-1607) 1G/2G polymorphism on the risk for developing oral cancer in the 1G allele European carriers." (PMID 23776649, 2013). "We also provide new information based upon our Puerto Rican oral cancer cases showing that the T allelic variant of the MMP-1 gene potentially promotes several microRNA binding sites." (PMID 24278120, 2013). "MMP1 has also been reported as a potential diagnostic and prognostic biomarker in oral cancer." (PMID 35444950, 2022). "Particularly in oral cancer, the studies are related to MMP-1, -2, -3 and -9 polymorphisms." (PMID 24455039, 2012). "The three (FAP, FN1, and MMP1) overexpressed genes show a significant potentiality for oral cancer development." (PMID 37936719, 2023). "To further verify the effectiveness of MMP-1 as a salivary biomarker for oral cancer detection, we used this in-house-developed ELISA to analyze levels of MMP-1 in 1160 clinical saliva samples from healthy subjects and patients with OPMD or OSCC." (PMID 32823758, 2020). "Upregulated expression of MMP-1 has also been reported in several types of cancer, including oral cancer." (PMID 32823758, 2020). "Our results based on tests of saliva samples from 131 oral cancer patients and 199 control cases showed that MMP-1 had a sensitivity of 69.5% and specificity of 95.0%, whereas CD44 had a sensitivity of 76.3% and specificity of 57.8%." (PMID 32823758, 2020). "Our findings confirm that the HAS2-mediated MMP1 and TIMP1 changes are most likely responsible for the mechanisms underlying CAF-mediated promotion of the migration, invasion and EMT of oral cancer cells." (PMID 27884164, 2016). "Fenofibrate inhibits the invasion and migration of CAL 27 oral cancer cells by suppressing the protein expressions of matrix metalloproteinase-1 (MMP-1), MMP-2, MMP-7, and MMP-9 through the AMPK and NF-κB signaling pathway." (PMID 26869356, 2016). "The present study analyzed the effects of EGF on the invasive activity of a cultured oral cancer cell line and assessed the transcription of MMP1." (PMID 24765152, 2014). "Involvement of S100A14 in the regulation of oral cancer cell proliferation and invasion, by modulating expression of several molecules including p21, MMP1 and MMP9, was reported by our recent studies." (PMID 24086685, 2013). "We chose three overexpressed genes (FAP, FN1, and MMP1) that could have potential regarding their presence in oral cancer patients." (PMID 37936719, 2023). "Thus, we present a novel approach to conjugate MMP-1 antibodies for targeting oral carcinoma cells followed by their cellular death via magnetothermal treatment." (PMID 35010011, 2021). "In summary, the data presented here demonstrate that HAS2, which is expressed by CAFs, may facilitate the migration, invasion and EMT of oral cancer cells by disturbing the balance between MMP1 and TIMP1." (PMID 27884164, 2016). "As EGF increased the invasiveness of the HSC-3 oral cancer cell line, it was assessed whether it is also likely to modulate the expression of MMP1." (PMID 24765152, 2014). "Indeed, MMP1 has been previously reported as consistently over-expressed in oral carcinoma compared to adjacent normal tissues and suggested as a biomarker of malignant transformation in precursor lesions in oral cancer." (PMID 21989116, 2011). "Therefore, in the treatment of OSCC, blocking the HPRT1/MMP1/PI3K/AKT axis might be an important approach to reverse resistance to CDDP in oral cancer." (PMID 35205603, 2022).
oral cancer (continued). "Moreover, the MMP1 gene might be used as a potential target to improve diagnosis and as an oral cancer marker for OSCC." (PMID 35909962, 2022). "A panel of five genes (MMP1, FBLN5, COL5A3, BGN and LOXL1) was useful for predication the successful grafters among oral cancer patients." (PMID 35444950, 2022). "Further studies will be required to understand the role of MMP1, PAR1 and PAR2 in oral cancer and oral cancer pain." (PMID 32895418, 2020). "Querying the TCGA HNSCC dataset we identified 8 potential mRNA targets (ESM1, KLF4, IL8, CCL20, IL24, CCNA1, TIMP4 and MMP1) from our validated 20 mRNA panel, which were aberrantly expressed in HNSCC and controlled by CELF1 in oral cancer cells." (PMID 26498364, 2015). "Thus, the matrix metalloproteinase-1 (MMP-1) antibody was modified on the surface of FeAu bimetallic NPs to act as a target for MMP-1 targeting high concentrations in and out of oral cancer cells." (PMID 35010011, 2021). "Thus, miR-196 appear to fine-tune the invasion mechanism in oral cancer by inhibiting NME4, leading to the activation of p-JNK and MMP1/9 and suppression of TIMP1." (PMID 25233933, 2014). "However, to our best knowledge, no studies have been carried out to examine the salivary MMP-1 levels in cancer patients other than oral cancer." (PMID 32823758, 2020).
chondrosarcoma (29 papers, 2007 to 2024). A malignant cartilaginous matrix-producing mesenchymal neoplasm arising from the bone and soft tissue. "Increased MMP-1 expression has been linked to poor outcome in chondrosarcoma patients and also promotes invasiveness of human chondrosarcoma cells in vitro." (PMID 29361725, 2018). "We further confirmed that the expression levels of HIF-2α were positively correlated with the levels of MMP1 in chondrosarcoma biopsies." (PMID 33024108, 2020). "The increases in IL-1β-treated human chondrosarcoma cell line SW1353 were 65.6% for MMP-1, 196.5% for MMP-3 and 119.3% for MMP-13." (PMID 33321982, 2020). "We demonstrated that this mode of binding is able to support biologically relevant bridging of the MMP to LRP-1, as TIMP-3 was able to promote MMP-1 endocytosis by HTB94 chondrosarcoma cells." (PMID 32694578, 2020). "The purpose of this study was to investigate the immunohistological expression of MMP-1, −3, −9, −13 in human chondrosarcoma and its correlation with metastatic potential as well as histological grading and survival of the patients." (PMID 29316907, 2018). "In consideration of semi quantitative scoring 64% of chondrosarcoma were scored as positive for MMP-1, 46% for MMP-3, 61% for MMP-9." (PMID 29316907, 2018). "Based on these results, BDNF appears to act via the TrkB receptor and the ASK1 and JNK/p38-dependent signaling pathways to enhance cell migration and MMP-1 production in human chondrosarcoma cells." (PMID 23892595, 2013). "Previous studies have shown significant expression levels of MMP-1, -2, -3, -9, and -13 in human chondrosarcoma cells." (PMID 24047437, 2013). "In human chondrosarcoma cell lines, MMP-1, MMP-2, MMP-3, MMP-9, and MMP-13 demonstrate increased expression." (PMID 23320110, 2013). "Our results indicate that BDNF enhances the migration and invasion activity of chondrosarcoma cells by increasing MMP-1 expression through a signal transduction pathway that involves the TrkB receptor, ASK1, JNK/p38, and Sp1." (PMID 23892595, 2013). "MMP-1 expression in chondrosarcoma cells correlates with cellular invasion and a transient down regulation of MMP-1 expression decreases cell invasion in vitro." (PMID 23799090, 2013). "In this study, we explored the involvement of the intracellular ASK1 signaling pathway in BDNF-induced MMP-1 production and cell migration in human chondrosarcoma." (PMID 23892595, 2013). "The results showed that BDNF-induced migration and invasion ability, as well as MMP-1 up-regulation of chondrosarcoma cells, were greatly reduced by pretreatment with the ASK1 inhibitor thioredoxin." (PMID 23892595, 2013). "We also found that BDNF increased cell motility and expression of matrix metalloproteinase-1 (MMP-1) in human chondrosarcoma cells." (PMID 23892595, 2013). "The results showed that BDNF binds to TrkB, which activates the ASK1, JNK/p38, and Sp1 pathways, leading to up-regulated MMP-1 expression, resulting in the promotion of migration of human chondrosarcoma cells." (PMID 23892595, 2013). "Of all MMPs, MMP-1 is the dominant metalloproteinase involved in the motility of human chondrosarcoma." (PMID 23892595, 2013). "CXCR4 signaling regulates the expression of matrix metalloproteinase 1 (MMP1), a marker of chondrosarcoma tissue invasion, metastasis, and poor prognosis." (PMID 21234386, 2011). "In chondrosarcoma, MMP1 is the dominant metalloproteinase that is expressed and is a marker for poor prognosis." (PMID 20102637, 2010). "The role of MMP1 in chondrosarcoma invasion and its role as a poor prognostic indicator have been known for some time." (PMID 20102637, 2010). "The present study determined the effect of hypoxia and specifically HIF-1a on expression of CXCR4 and MMP1 and their role in chondrosarcoma cell invasion." (PMID 20102637, 2010). "Factors such as MMP1 mediate local migration out of the microenvironment, ie stroma for carcinoma and bone for chondrosarcoma, and into the circulation." (PMID 20102637, 2010).
chondrosarcoma (continued). "Quantitative RT- PCR was used to quantitate the MMP1 mRNA in human chondrosarcoma cells and in adjacent stromal cells following isolation by laser capture microdissection." (PMID 21170377, 2010). "In order to determine the target cell population for MMP1 silencing, we carried out an expressional analysis of MMP1 in human chondrosarcoma specimens by both laser capture microdissection and in situ hybridization." (PMID 21170377, 2010). "Hypoxia and specifically HIF-1a increased CXCR4 and MMP1 expression in JJ cell line and chondrosarcoma invasion in vitro." (PMID 20102637, 2010). "Earlier results from our laboratory indicate a prognostic significance of MMP1 expression in disease specific survival of patients with chondrosarcoma." (PMID 21170377, 2010). "Previously, we reported the prognostic significance of MMP1 gene expression in patients with chondrosarcoma." (PMID 21170377, 2010). "We have shown that one mechanism of increased MMP1 in chondrosarcoma is mediated through CXCR4 signaling, which is amplified by hypoxia, and is mediated by ERK, but not other MAP kinases." (PMID 20102637, 2010). "We present data that shows hypoxia mediated increase in MMP1 expression and chondrosarcoma invasion is partially mediated by CXCR4 signaling." (PMID 20102637, 2010). "We also show that increased CXCR4 signaling regulates expression of MMP1, a factor known to be involved with chondrosarcoma metastasis and a marker for poor prognosis." (PMID 20102637, 2010). "However, TNC was reported to induce MMP-1 expression via MEK1 activation in chondrosarcoma cells and activate ERK, JNK, and p38 MAPK, and integrin β1 and β3 in airway smooth muscle cells." (PMID 33217999, 2020). "MMP-1, -2, -3, -9 and -13 were expressed in human chondrosarcoma cells." (PMID 30237403, 2018). "Some individual chondrosarcomas also exhibited elevated levels of MMP-1, MMP-7 and MMP-9 mRNAs." (PMID 29316907, 2018). "Moreover, transfection of cells with ASK1 shRNA inhibited BDNF-induced motility and MMP-1 expression in chondrosarcoma cells." (PMID 23892595, 2013). "Indeed, several lines of evidence in the current study confirmed that MMP-1 is involved in BDNF-induced cell migration of human chondrosarcoma cells." (PMID 23892595, 2013). "Therefore, our results provide evidence that BDNF up-regulates MMP-1 expression and cell migration in human chondrosarcoma cells via the ASK1 and JNK/p38 signaling pathways." (PMID 23892595, 2013). "Moreover, MMP-1 has been found to play a role in the ECM degradation associated with cancer metastasis, and is therefore a prognostic factor for human chondrosarcoma." (PMID 23892595, 2013). "Therefore, activation of the TrkB receptor and the ASK1, JNK/p38, and Sp1 pathways are required for BDNF-induced cell migration and MMP-1 production in human chondrosarcoma cells." (PMID 23892595, 2013). "MMP-1, −2, −3, −9, and −13 have been found to regulate metastasis of human chondrosarcoma." (PMID 23320110, 2013). "All three are in the “multifunctional” signature of dedifferentiated chondrosarcoma lung metastases—MMP1 and CXCL1 were significantly differentially expressed in 4 out of 5 metastases; TNC was differentially expressed in all 5 metastases and it is also a component of the “biased” signature)." (PMID 22448124, 2012). "Inhibition of MMP1 with siRNA has been shown to decrease chondrosarcoma cell invasion." (PMID 20102637, 2010). "The expression MMP1 is a prognostic factor in human chondrosarcoma, however the role in tumor progression is unknown." (PMID 21170377, 2010). "The hypoxia mediated increase in MMP1 expression and chondrosarcoma invasion could be inhibited by siRNA directed at HIF-1a or CXCR4, the CXCR4 inhibitor AMD3100, as well as with ERK inhibitor U0126 and ERK siRNA." (PMID 20102637, 2010).
chondrosarcoma (continued). "However, this project is the first to link the combined effects of HIF-1a on CXCR4 and MMP1 expression and the indirect effect of HIF-1a on MMP1 expression acting through CXCR4, which independently increases MMP1 in chondrosarcoma cells." (PMID 20102637, 2010). "The mechanism of increased MMP1 expression in chondrosarcoma is not completely known." (PMID 20102637, 2010). "Indeed in this study MMP-1, −3, −9 were found in the majority of the chondrosarcoma specimens." (PMID 29316907, 2018). "However, the role of ASK1 activation in MMP-1 expression and cell motility in human chondrosarcoma is largely unknown." (PMID 23892595, 2013). "However, the mechanisms of increased MMP1 expression in chondrosarcoma are incompletely understood." (PMID 20102637, 2010). "Our results showed that NUC1 treatment inhibited the extracellular release of MMPs by blocking TNF-α-induced MMP-1, MMP-3, and MMP-13 expression in chondrosarcoma cells." (PMID 37482815, 2023). "This study demonstrated that NUC1 inhibited the production of NO in LPS-induced macrophages, and reduced MMP-1, MMP-3, and MMP-13 levels in chondrosarcoma cells treated with TNF-α." (PMID 37482815, 2023). "NUC1 also inhibited the release and protein expression of MMP-1, 3, and 13, in TNF-α-induced chondrosarcoma cells in a concentration-dependent manner." (PMID 37482815, 2023). "Relative to the levels for IL-1β-treated human chondrosarcoma cell line SW1353, the expressions of MMP-1, MMP-3 and MMP-13 were decreased dose dependently in the 20 μg/mL CZE and 0.4 μg/mL linarin treatment." (PMID 33321982, 2020). "We first verified that transcriptional expression of MMP1, MMP3, MMP13, and ADAMTS4 was upregulated by IL-1β or TNF-α and repressed by I-BET151 in a human chondrosarcoma cell line (SW1353)." (PMID 30786900, 2019). "The purpose of this study was to investigate immunohistochemicaly the influence of MMP-1, MMP-3, MMP-9 and MMP-13 expression on prognostic parameter in chondrosarcoma." (PMID 29316907, 2018). "Expression levels of MMP-1, MMP-2, MMP-3, MMP-7, MMP-8, MMP-9, and MMP-13 are high in human chondrosarcoma cells." (PMID 30237403, 2018). "Previous studies have demonstrated the expression of MMP-1, MMP-2, MMP-3, MMP-9, and MMP-13 in human chondrosarcoma cells." (PMID 24047437, 2013). "Studies have shown that MMP-1, MMP-2, MMP-3, MMP-9, and MMP-13 exhibit high degrees of expression in human chondrosarcoma cells." (PMID 23892595, 2013). "It was also recently published that A-SAA increased MMP-1, MMP-3 and MMP-13 mRNA and protein expression levels on human chondrosarcoma cells SW1353 and human primary chondrocytes provided from normal articular cartilage." (PMID 23776697, 2013). "A previous study showed that MMP-1, MMP-2, MMP-3, MMP-9, and MMP-13 were expressed in high quantities in human chondrosarcoma cells." (PMID 23892595, 2013). "Chondrosarcoma cell invasion is increased by hypoxia induced expression of CXCR4 and MMP1 and is mediated by HIF-1a and ERK." (PMID 20102637, 2010). "We recently described the ability of retinoid X receptor (RXR) ligand LG100268 (LG268) to inhibit interleukin-1-beta (IL-1-β)-driven matrix metalloproteinase-1 (MMP-1) and MMP-13 gene expression in SW-1353 chondrosarcoma cells." (PMID 19046432, 2008). "We show that the effect of combined treatment on MMP-1 and MMP-13 is observed at the protein level, where the addition of both ligands leads to decreased collagen destruction by IL-1β-activated SW-1353 chondrosarcoma cells over single-ligand treatment." (PMID 19046432, 2008). "Similar to OS and ES, the expression of MMPs such as MMP-1, MMP-2, MMP-3, MMP-7, MMP-9, and MMP-14 is also found in biopsy specimens from patients with chondrosarcoma." (PMID 38138968, 2023). "Moreover, MMP-1, MMP-7 and MMP-9 expression was found to be highest in the invasive protrusions of chondrosarcomas." (PMID 29361725, 2018). "MMP-1, MMP-2, MMP-3, MMP-7, MMP-9 and MMP-13 are frequently expressed in chondrosarcoma tissues." (PMID 29361725, 2018).
chondrosarcoma (continued). "In conclusion, MMP-1, MMP-3 and MMP-9 are often expressed in chondrosarcoma." (PMID 29316907, 2018). "In consideration of semiquantitative scoring 64% of chondrosarcoma were scored as positive for MMP-1, 46% for MMP-3, 61% for MMP-9 and no for MMP-13." (PMID 29316907, 2018). "Up-regulation of MMP-1 and MMP-13 by IL-1β was previously demonstrated in chondrosarcoma cells." (PMID 24901233, 2014). "Previous studies have shown that HA (800 kDa and higher) suppressed IL-1β-stimulated production of collagenases (MMP-1 and MMP-13) by human articular cartilage explants and isolated chondrocytes, as well as a human chondrosarcoma cell line, through down-regulation of phospho-p38 MAPK." (PMID 23889808, 2013). "The current study demonstrated that BDNF increases MMP-1 expression by binding to the TrkB receptor and activating the ASK1, JNK/p38, and Sp1-dependent pathways, thereby enhancing the migration and invasion activity of human chondrosarcoma cells." (PMID 23892595, 2013). "Interestingly, chondrosarcoma cell invasion is increased by hypoxia-induced expression of CXCR4 and MMP1, a process mediated by HIF1α and ERK, and CXCL12, also called SDF-1, increases the invasiveness of chondrosarcoma cells." (PMID 21647363, 2011). "Chondrosarcoma is a disease that does not respond to conventional cytotoxic chemotherapy and expression of MMP1 is a marker for a poor prognosis." (PMID 20102637, 2010). "CXCR4 blockade can inhibit the effects of hypoxia on MMP1 expression and chondrosarcoma invasion in vitro, suggesting that CXCR4 blockade could be a therapeutic target to inhibit chondrosarcoma invasion and metastasis." (PMID 20102637, 2010). "Both invasion and MMP1 can be inhibited with CXCR4 blockade, suggesting that CXCR4/SDF1 signaling may be a therapeutic target for chondrosarcoma." (PMID 20102637, 2010). "Interestingly, some studies indicate the prognostic potential of the MMP-1/TIMP-1 ratio—patients with recurrent chondrosarcoma have shown higher values of the MMP-1/TIMP-1 ratio than patients without recurrence." (PMID 38138968, 2023). "However, this mode of binding appears to be insufficient to support bridging to LRP-1 in a complex biological environment, as we found that neither TIMP-1 nor TIMP-2 could increase the rate of MMP-1 endocytosis by HTB94 chondrosarcoma cells." (PMID 32694578, 2020). "MMP-1 and MMP-3 expression in IL-1β-stimulated chondrosarcoma cells was suppressed by p38 and ERK inhibitors but not by JNK inhibitor, and MMP-13 expression was suppressed by p38 and JNK inhibitors but not ERK inhibitor." (PMID 32213810, 2020).